PDGFRA (platelet derived growth factor receptor alpha)
Diseases named in the same sentence as PDGFRA in open-access papers (continued):
Sharing a sentence is not in itself a finding about the gene and the disease.
cancer (continued). "Our TCGA database analysis suggested that PDGFRα upregulation was positively correlated with the activation of the PI3K-AKT signaling pathway in human cancers." (PMID 33568640, 2021). "PDGF, a ligand of PDGFRA, promotes cancer angiogenesis in the cancer stroma and has positive regulation of cell proliferation and angiogenesis by VEGF-activated PDGFRA." (PMID 34702313, 2021). "Kinases that were rarely mutated, including MET, PIK3CB, and PDGFRA/PDGFRB, were found to be substantially overexpressed at the protein level in the same cancer types." (PMID 34552204, 2021). "Among these genes, 18 cancer driver genes showed a dual role associated with epigenetic changes, five of which were considered to be critical: SLC27A6, PDGFRA, GAS7, PLXNC1, and NRP2." (PMID 31900418, 2020). "Further support for a fundamental role of miR-710 in cancer derives from the fact that its predicted targets include ADAM10, PDGFRA, and FZD7, which are linked to senescence and stemness." (PMID 31834924, 2019). "The bioinformatics analyses suggest stronger global cancer network rewiring in NTRK HGG than PDGFRA HGG, indicating higher oncogenic potency of NTRK than PDGFRA mutations." (PMID 31420543, 2019). "Anti-cancer agents targeting PDGFRA include receptor tyrosine kinase (RTK) inhibitors such as imatinib, sunitinib, and dasatinib." (PMID 31185958, 2019). "It was reported that PDGFRα signaling is upregulated in cancer cells due to an elevated amount of PDGFRα." (PMID 27293550, 2016). "By showing that SMARCB1 loss also regulates PDGFRα expression levels, our study provides further evidence that exploiting RTK dependencies in cancers driven by SWI/SNF deficiencies is an effective therapeutic strategy in vitro." (PMID 27783942, 2016). "Aberrant activation of PDGFRα signaling has been observed in several human cancers including ovarian, melanoma, gastrointestinal stromal tumors, glioblastoma, prostate, breast, lung, renal cell and sarcoma." (PMID 27845909, 2016). "Since it is less likely for cancer cells to develop acquired resistance when multiple RTKs are simultaneously inhibited up front, there is a rationale for using the PDGFRα and FGFR1 inhibitor combination as first-line therapy." (PMID 27783942, 2016). "It is widely accepted that PDGFRα is activated in various cancers and serves as a potential therapeutic target." (PMID 25333264, 2014). "Dysregulation of platelet-derived growth factor receptor alpha (PDGFRα) has been documented in various cancers." (PMID 25333264, 2014). "PDGFRα is a type III receptor tyrosine kinase and genetic mutations have been reported in many human cancers." (PMID 25372838, 2014). "Gastrointestinal mesenchymal tumors identified by the Modena Cancer Registry between 1991 and 2004 were analyzed with an immunohistochemical panel that included staining for CD-117 and PDGFRα." (PMID 18096058, 2007). "Using normal serous epithelium as a reference, decreased PDGFRA expression was detected in 12% and increased expression in 13% of carcinomas." (PMID 15583695, 2004). "Targeting PDGFA/PDGFRA signaling could represent a therapeutic opportunity to treat fibrosis-related disorders and cancer." (PMID 40892943, 2025). "Additionally, PDGFRA, a receptor tyrosine kinase essential for cell proliferation and survival, exhibits decreased expression in cancer." (PMID 40817072, 2025). "PDGFRα/β could therefore serve as promising targets for direct anti-cancer therapy in treating these cancers." (PMID 39780187, 2025). "How PDGFRα is specifically trafficked to the older cilia, and how cancer cells might benefit from this, is a fascinating question." (PMID 40301543, 2025).
cancer (continued). "Moreover, enhanced levels of all CAF-related proteins such as PDGFRα, PDGFRβ, and FAP are reportedly associated with cancer invasiveness and more likely to be found in HER2 subtypes than in TNBC." (PMID 39858015, 2025). "Most literature about PDGFRα’s role in angiogenesis is related to cancer research." (PMID 38673853, 2024). "Cancer patients suffering from PDGFRA-D842V-driven GIST have limited treatment options." (PMID 38167404, 2024). "Platelet-derived growth factor alpha (PDGFRA) plays a significant role in various malignant tumors." (PMID 39850565, 2024). "Only MT-ND2 and PDGFRA were consistently downregulated across all five cancer types." (PMID 39594421, 2024). "At the cell level, the exposure of phosphotyrosine epitopes of PDGFRA on the cell surface may make the cancer cells distinctive from the normal hepatocytes immunologically." (PMID 39082961, 2024). "PDGFRA and COL1A1 were universally expressed in three commercially cancer associated fibroblasts." (PMID 39034310, 2024). "Moreover, the levels of lncXIST, miR-17-ap, and PDGFRA should also be evaluated in the treated cancer cells." (PMID 39518984, 2024). "Moreover, PDGFRA amplification was correlated with the shorted overall survival in pan‐cancer TCGA datasets." (PMID 36043552, 2023). "Some of the PDGFRα+ cancer-derived fibroblasts surrounding gastroids also expressed PDGFRβ, as observed in fibroblasts adjacent to epithelial cells in cancer tissues." (PMID 37196797, 2023). "Targeting the PDGFRA axis has been demonstrated to be an effective cancer therapeutic strategy." (PMID 37673888, 2023). "Furthermore, we exprlored the expression of marker genes (PDPN, THY1, PDGFRB, PDGFRA,and POSTN) for cancer-associated fibroblasts (CAFs) in different cell types, and found that all marker genes were highly expressed in fibroblasts." (PMID 36973787, 2023). "Likewise, while association of the CN gain in PDGFRA pathway with higher TMB and TNB values was identified in ACC, LUAD and some other types of cancers, the association was in the opposite direction in UCEC." (PMID 35212838, 2022). "The frequency of CN gains in PDGFRA pathway ranged from 1 to 45% among various cancer types." (PMID 35212838, 2022). "It is therefore crucial to select PDGFRA inhibitors that are effective in cancer treatment." (PMID 36685223, 2022). "In this study, we analyzed the distribution of PDGFRA pathway CN gain in pan-cancer patients based on information from the TCGA database and investigated the association of PDGFRA pathway CN gain with tumorigenesis-related pathways, immune cell subpopulations, and survival rates." (PMID 35212838, 2022). "Moreover, we observed that the CN gain of PDGFRA pathway was associated with a higher proportion of LOH alterations and higher CNV burden in most cancers such as KIRC, LUAD, SKCM, and UCEC, while the association was in the opposite direction in ACC." (PMID 35212838, 2022). "Furthermore, risk score was linked to immune checkpoint expression (including PD-L1, CTLA4), targeted therapy gene expression (PARP, PDGFRA), cancer stem cell (CSC), chemotherapy and targeted medication sensitivity." (PMID 36307842, 2022). "In our study, we found that patients with high PDGFRA expression had better survival outcomes than those with low PDGFRA expression, which appears to conflict with the common theme in other types of cancer in which high expression of PDGFRs is correlated with poor prognosis." (PMID 35378770, 2022). "In this study, we show that SIRT6 deficiency increases the nuclear ACLY protein, nuclear acetyl-CoA abundance, and locus-specific histone acetylation, which in turn drive an up-regulation of PDGFRA and other genes that contribute to invasive cancer cell adhesion and migration phenotypes." (PMID 34573442, 2021). "Importantly, this group of fibroblast cells expressed the markers for cancer‐associated fibroblasts (CAFs) including ACTA2 (encoding α‐SMA), PDGFRA, PDGFRB, DDR2, FAP, and CAV1." (PMID 34459128, 2021).
cancer (continued). "Therefore, PDGFRα expression positively correlated with PI3K-AKT pathway activity in human cancer tissues." (PMID 33568640, 2021). "We found that while almost all cancer cells expressed OPC-associated signal transduction factors OLIG1, OLIG2, and PDGFRA, expression of progenitor-associated transcription factors such as SOX2 and SOX10 were highly expressed in cells expressing the MAPK programme." (PMID 31427603, 2019). "Interestingly, several reports suggested a critical crosstalk between ILC2s and Platelet Derived Growth Factor Receptor Alpha (PDGFRa) with the latter being an established player in the context of fibrosis, tissue repair, and cancer." (PMID 31574995, 2019). "This opens new areas for therapeutic intervention that were otherwise not ascribed to PDGFR signaling where drug sensitivities may occur in a conditional (e.g., PDGFRα-positive cancers) manner." (PMID 30456354, 2018). "PDGF-CC is a member of the platelet-derived growth factor (PDGF) family that stimulates PDGFRα phosphorylation and thereby activates intracellular signalling events essential for development but also in cancer, fibrosis and neuropathologies involving blood-brain barrier (BBB) disruption." (PMID 30052660, 2018). "PDGFRα allows isolation of both normal and cancer-associated fibroblasts, including but not restricted to αSMA+ activated fibrolasts." (PMID 29211796, 2017). "In addition, a previous study demonstrated that overexpression of PDGFRα in Hep3B promoted cell proliferation, migration and invasion that are hallmarks of cancer cells." (PMID 28465473, 2017). "Module 5 contains known EMT inducers ZEB1, SNAI2, and TCF4 (E2.2), as well as multiple other genes known to be important in focal adhesion, extracellular matrix interaction, extracellular matrix organization, and markers of cancer-associated fibroblasts (PDGFRB, PDGFRA)." (PMID 27287041, 2016). "If this hypothesis is true, it could be possible that cancer with a high PDGFRα amount is characterized by downregulated mTOR signaling." (PMID 27293550, 2016). "Somatic PDGFRA loss-of-function mutations were recently characterized in cancers, but they likely represent passenger mutations that are not clinically relevant." (PMID 25292412, 2015). "Since persistent STAT activation often occurs in cancer, we were interested whether the oncogenic activation of PDGFRα also leads to the activation of STAT1, STAT3 and STAT5 transcription factors." (PMID 25880691, 2015). "While analysis the PDGFR specific signatures in MB tumors, we noticed the results from 2 out of 5 data sets showing that PDGFRβ, but not PDGFRα, was associated with miRNA_in_cancer." (PMID 25576913, 2015). "Given a critical role of PDGFRα in caner growth and metastasis, our finding of BRD4 epigenetic control of PDGFRα may lend important insights for cancer research as well." (PMID 26870791, 2015). "Furthermore, CNAs, as often reported in clinical samples, were detected in the regions of some cancer-related genes; for example, copy number gains of FGFR1, EGFR and PDGFRA in H1703, amplification of MYC and a homozygous loss of CDKN2A in LC2/ad." (PMID 25378332, 2014). "This led to our investigation of co-expression of PDGFRα and EpCAM using cancer cell lines." (PMID 23990866, 2013). "For example, PDGFA and PDGFRA of the PDGF signaling pathway are targeted by approved drugs for other cancers and potentially could be exploited for use in ESCC." (PMID 22280838, 2012). "There are examples of cancer mutations displaying a subgroup level of conservation, including EGFR-L858 position, which bears a conserved leucine in EGFR and ABL kinases, or a conserved aspartate shared in FLT3, KIT, MET, PDGFRα." (PMID 19834613, 2009). "A number of intronic and exonic variations but no known mutations in the coding sequence of the PDGFRα gene were found in cancer cell lines and primary tumors." (PMID 17014709, 2006).
cancer (continued). "Furthermore, CAF-derived PDGFC promotes epithelial-mesenchymal transition (EMT) in cancer cells as well as matrix metalloproteinase 2 (MMP2) expression through the PDGF receptor A (PDGFRA)-mitogen-activated protein kinase/extracellular signal-regulated kinase (MAPK/ERK) pathway." (PMID 40501228, 2025). "Our findings also suggest that similar PDGFA/PDGFRA signaling mechanisms may be employed in other contexts, such as recruiting fibroblasts during wound healing or regulating cell migration in pathological conditions like cancer metastasis." (PMID 40892943, 2025). "Notably, this included TGF-β (TGFB1, TGFB3), drivers of adenosine-mediated immune suppression (NT5E (CD73), ENTPD1 (CD39)), Wnt pathway ligands (WNT7A, WNT4), IL10 and drivers/markers of cancer-associated fibroblast activation (INHBA, WNT7A, TGFB1, FAP, PDGFRA, PDGFRB)." (PMID 39568014, 2024). "PDGFRA may be an anti-cancer drug target in gastrointestinal cancer." (PMID 35896848, 2022). "Thus, PDGFRA inhibitors are critical to developing drugs and cancer treatment." (PMID 36685223, 2022). "In conclusion, PDGFRA pathway CNV gain may be a poor prognostic factor in cancer patients." (PMID 35212838, 2022). "However, PDGFRA amplifications are among the most common genetic alterations in cancer." (PMID 34312479, 2021). "In the era of precision medicine, cancer genome profiling by targeted gene panel analysis may enable potential targeted therapy even for GISTs without KIT or PDGFRA mutations." (PMID 34202544, 2021). "Interestingly, KDR, besides the 10-fold overexpression in the cancer cells from the PDGFRA#4 and #6 cases with gene amplification, showed mild to moderate overexpression without gene amplification, with a 7.7-fold upper range, in the majority of cases from many subgroups." (PMID 34572759, 2021). "Increased PDGFRα mRNA was also associated with increased lecithin retinol acyltransferase (Lrat), which is the marker for both activated and quiescent HSCs, and elevated smooth muscle α-actin (αSMA) expression, which is known as the marker for activated HSC and cancer-associated fibroblast." (PMID 28465473, 2017). "Because many receptor proteins (e.g., EGFR, PDGFRA, PDGFRB, ERBB2, and ERBB4) are typically located in the upstream of cancer-related signaling pathways such as proliferation, cell death, and cell cycle progression, mutations in these genes are likely critical to cancer development." (PMID 24516372, 2014). "Furthermore, with exception of GISTs, the presence of overexpression of KIT and PDGFRA in human cancers was not correlated with presence of activating mutations." (PMID 23497641, 2013). "We suggest that defects in ciliary formation due to over-expression and centrosomal localization of AURA in cancer OSE cells in a similar way may perturb proper Hh signaling as well as PDGFRα expression and function leading to homeostatic imbalance of the ovarian surface epithelium." (PMID 23351307, 2012). "Using the OncoGuide NCC Oncopanel System (114 genes) and FoundationOne CDx Cancer Genomic Profile (324 genes), they identified alterations in KIT (78%), PDGFRA (6%), and SDHB (6%)." (PMID 41355515, 2025). "PDGFRA and PIK3 CA, both important for cell growth and survival signaling, when down-regulated, can disrupt these pathways, promoting cancer through alternative oncogenic mechanisms." (PMID 40450370, 2025). "In summary, our investigation into the role of immune-related genes, including COL1A1, ITGB1, THY1, and PDGFRA, in UCEC sheds light on their multifaceted contributions to cancer development and progression." (PMID 40817072, 2025). "Other known recurrent cancer genes with ≥10 occurrences include PLEC, PDGFRA, NF1, ARID1A, BCOR, and ACVR1." (PMID 41312385, 2025). "To assess the clinical relevance of COL1A1, ITGB1, THY1, and PDGFRA genes in UCEC progression, we examined the correlation between their transcriptional expression levels and cancer stages." (PMID 40817072, 2025).
cancer (continued). "PDGFRα, the primary receptor for PDGFC, was inhibited using a PDGFRα inhibitor, which effectively suppressed the ability of cancer cell-CM to promote NRG1 expression in fibroblasts." (PMID 41213930, 2025). "These variants were found in over 45% of the cohort and occurred in genes with known relevance to cancer biology, including CHEK2, RAD54L, NOTCH2, ASXL1, PDGFRA, and KIT." (PMID 40627234, 2025). "This panel included PDGFR-α (platelet-derived growth factor receptor alpha) and CDH20 (cadherin 20); both were significantly upregulated in MSCs compared to cancer cell lines." (PMID 39621192, 2025). "Constitutively active forms of PDGFRA, FGFR3, and TRKA are found in the Golgi/TGN region and are autophosphorylated in cancer cells." (PMID 40770227, 2025). "Recent studies have reported that RTKs other than KIT, such as FLT3-ITD, PDGFRA, MET, and insulin-like growth factor receptor 1 (IGF-1R), also use the Golgi/TGN as their signaling platform in cancer cells." (PMID 38679330, 2024). "The analysis of heatmaps revealed that PDGFRA and PTPRR demonstrated high SNV across various cancers, whereas PTPRR and RAC3 exhibited elevated CNV in the majority of cancer types." (PMID 38714855, 2024). "These included, but were not limited to: PECAM1 and CDH5 (EC markers), PDGFRA (fibroblast marker), PDGFRB (pericyte marker), and EPCAM and KRT18 (cancer cell markers)." (PMID 38183074, 2024). "Although our results show that ponatinib (PDGFRA inhibitor) is more effective than sunitinib (PDGFRB inhibitor) in reducing growth and migration of the cancer cells, both inhibitors were capable of suppressing cell proliferation and migration." (PMID 36979654, 2023). "The molecular consequence of activated PDGFRA is exemplified through enhanced PI3K/AKT-, JAK/STAT-, and MAPK-pathway activity contributing to cancer-cell survival and overall disease severity." (PMID 37681903, 2023). "Biomarkers (FAP, POSTN, PDGFRα/β, FSP-1, CD90, Palladin, OPN, AEBP1, TNC, CD10, and GPR77) represent cancer-promoting CAFs." (PMID 37476379, 2023). "The genomic alterations of PDGFRA, PARP1, CREBL2, and DAB1 cooperatively contributed to the abnormality of cancer hallmarks." (PMID 37491836, 2023). "PDGFRA and PDGFRB have 0.49 and 0.53 of the correlation coefficiency for ERG expression, respectively, in S:E fusion-positive cancer." (PMID 36579559, 2022). "The expression of PDGFRA, a marker of mesenchymal cells, was negatively correlated with EXTEND scores in 21 of 31 cancer types." (PMID 33420056, 2021). "PDGFRA mRNA was undetectable in MDA-MB-231 and MCF-7 cells as expected from the Cancer Cell Line Encyclopedia." (PMID 34575976, 2021). "For example, in urologic cancer, common genes regulated by prognosis-alternative miRNAs such as BCL2, EGFR, KIT, PDGFRA, and VEGFA, have been validated as anti-cancer drug targets previously." (PMID 32523951, 2020). "In neuronal cells, the cancer-related gene SLIT2 was found to be upregulated, as were six other cancer-related genes (PDGFRA, DDR2, RSPO3, IL6ST, NTRK2, and HEY1) in cardiomyocytes and one cancer-related gene (HSD3B1) in hepatocyte-like cells." (PMID 32127560, 2020). "For the mass cytometry assay, PDGFRA and OLIG2 were included as markers for progenitor cancer cells." (PMID 32641768, 2020). "Platelet-derived growth factor receptor alpha (PDGFRA), which had the highest evaluation score, was identified as the target of one HCC drug (Regorafenib), five cancer drugs, and four non-cancer drugs." (PMID 32497121, 2020).